P4HA1 (prolyl 4-hydroxylase subunit alpha 1)
Diseases named in the same sentence as P4HA1 in open-access papers (continued):
Sharing a sentence is not in itself a finding about the gene and the disease.
cancer (continued). "Likewise, P4HA1 is the active catalytic component of prolyl 4-hydroxylase and has been reported to promote tumor progression and metastasis in several cancers." (PMID 33747908, 2021). "Previously, it has been shown that P4HA1 stabilizes hypoxia-inducible factor 1α (HIF1α) by modulating the levels of its glycolytic substrates, α-ketoglutarate, and succinate, thus mediating cellular transformation of cancer cells." (PMID 34337075, 2021). "P4HA1 located in the cytoplasm and membrane of cancer cells, and rarely identified in nucleus." (PMID 34659558, 2021). "Therefore, we used different immune cell infiltration data to analyze the correlation between P4HA1 expression and immune cell infiltration in pan-cancer." (PMID 34966739, 2021). "Reports suggest P4HA1 and P4HA2 to be associated with cancer proliferation and hypoxic regulation." (PMID 33692831, 2021). "Due to P4HA1 role in mediating high collagen deposition in tumor microenvironment and progression, new therapeutic strategies or small molecule inhibitors are under development to target collagen synthesis for cancer therapy." (PMID 34966739, 2021). "Aberrant P4HA1 expression affects tumor progression in several malignant tumors." (PMID 33952718, 2021). "Therefore, previous studies showed that P4HA1 played an important role in the process of malignant tumor progression." (PMID 33415167, 2020). "In this study, a brief pan-cancer analysis of P4HA1 in various tumors was first conducted." (PMID 33415167, 2020). "It has been shown that P4HA1 expression is induced during cancer development and progression." (PMID 32927660, 2020). "Up-regulation of P4HA1 has been reported in some other cancers." (PMID 32166002, 2020). "Furthermore, in our study the mRNA level of the LGR5 transcript variants were positively correlated with the mRNA level of CTGF, P4HA1, and IGF2, as all of these genes are linked to metastasis in cancer." (PMID 30770730, 2019). "We further demonstrated that P4HA1 regulates cancer cell stemness through the HIF-1 pathway." (PMID 31225497, 2019). "Collectively, P4HA1 may regulate cancer cell stemness through HIF-1-dependent metabolic reprogramming." (PMID 30367042, 2018). "Our study shows that targeting the enzyme P4HA1 through small molecule inhibitors can achieve results similar to MMP inhibitors in cancer and could be a promising novel therapeutic option." (PMID 25115393, 2014). "In addition to this, P4HA1 immune-modulatory role in cancer has been only recently analysed in different cancer types where its increase associated with worse cancer prognosis and lower overall survival, correlates with an immunosuppressive TME and reduced anti-tumoral response." (PMID 39828692, 2025). "Finally, we investigated whether CAF/LA-induced P4HA1 expression contributes to cancer cell colonizing behavior." (PMID 38907027, 2024). "P4HA1 mediated high collagen deposition plays a crucial role in the tumor microenvironment and progression, and new therapeutic strategies or small-molecule inhibitors targeting collagen synthesis are being developed, which will be an important direction for future cancer research." (PMID 39568592, 2024). "Therefore, we need to comprehensively explore the roles of P4HA1 in human cancers." (PMID 35812752, 2022). "As a result, targeting P4HA1 may be potential cancer immunotherapy." (PMID 34966739, 2021). "Because P4HA1-mediated high collagen deposition is critical in tumor microenvironment and progression, new therapeutic strategies or small molecule inhibitors are under development to target collagen synthesis for cancer therapy, which will be an important direction of cancer research in the future." (PMID 34966739, 2021). "However, the immunomodulatory role of P4HA1 in pan-cancer is insufficient." (PMID 34966739, 2021). "Interestingly, P4HA1 expression is upregulated in cancer stem cell enriched cell population." (PMID 31225497, 2019).
cancer (continued). "However, we know little about how expression of P4HA1 in cancer cells promotes tumor progression." (PMID 31225497, 2019). "However, we know little about how cancer cell P4HA1 promotes tumor progression." (PMID 30367042, 2018). "Therefore, inhibition of P4HA1 may sensitize TNBC to chemotherapeutic agents by inhibiting cancer cell stemness." (PMID 30367042, 2018). "However, roles of P4HA1 in HER2 cancer progression still need further clarification." (PMID 30367042, 2018). "However, few studies have focused on the function of P4HA1 in cancers until recently." (PMID 28415787, 2017). "Therefore, we focused on the function of P4HA1 and its role in cancer." (PMID 28415787, 2017). "Given the scarce reports on P4HA1 function in CRC, our data provide novel insights into its contribution to cancer pathogenesis." (PMID 40959429, 2025). "P4HA1 and 2 play a central role in collagen synthesis, EMT, collective cancer cell migration and angiogenesis." (PMID 40867253, 2025). "Whether the down-regulation of Hspa1b, P4ha1, and Banp genes in whole blood and in the hippocampus in the present study is involved in the body’s self-protective mechanism in preventing low dose rate irradiation-induced early-life stress and cancers remains unknown." (PMID 39272995, 2024). "By modulating alpha-ketoglutarate (α-KG) and succinate levels, P4HA1 expression reduces proline hydroxylation on HIF-1α, enhancing its stability in cancer cells." (PMID 38544822, 2024). "Prolyl 4-hydroxylase subunit alpha 1 (P4HA1), the catalytic subunit of collagen prolyl 4-hydroxylase, is a glycolysis-related gene in cancers." (PMID 38238754, 2024). "Both PLOD2 and P4HA1 are enzymes involved in collagen-related pathways and proved to be a biomarker of epithelial-to-mesenchymal transition (EMT) in multiple types of cancers." (PMID 36901940, 2023). "Taken together, our data uncovered that the aberrant expression of P4HA1 is correlated with clinical prognosis, immune cell infiltration, DNA methylation, TMB, and MSI in multiple cancer types." (PMID 35812752, 2022). "For example, knockdown of P4HA1 and P4HA2 in prostate and breast cancer, respectively, reduced cancer cell proliferation, invasion, and metastasis, both in vitro and in vivo." (PMID 35804902, 2022). "The role of P4HA1 in PDAC was revealed, which can regulate HIF1α activity and led to high proliferation, chemoresistance, and cancer cell stemness." (PMID 36291742, 2022). "The corresponding heatmap analysis also indicated a positive correlation between P4HA1 and these five genes (BNIP3L, FUT11, LDHA, PGK1, and RPL17P50) in the majority of 32 types of cancers." (PMID 35812752, 2022). "Our discovery of P4HA1 outcome stratification in early stage CRC and, in particular, its MSS subtype, may provide an avenue for early stage CRC risk prognosis and thus improve cancer treatment outcomes by tailoring follow-up frequency and adjuvant therapy intensity." (PMID 32166002, 2020). "A recent study showed a signature involving P4HA1, PLOD1, KDM3A, PLOD2, and ASPH predicted prognosis in various cancers including LUAD using bioinformatic analysis." (PMID 33299876, 2020). "And most of the 24 DEPs (CDK1, SFN, PRKAR2B, MKI67 and MDK involved in the cell cycle; LOXL2, P4HA1, P4HA2, SPRX, DES, PRPH and CALML3 involved in construction and regulation of extracellular matrix; IL33 and EHD3 may involve in immune) were linked to cancer hallmarks." (PMID 33200655, 2020). "TUBA1C (r was range from 0.29 to 0.66), TUBA1B (0.21~0.65), P4HA1 (0.25~0.74), HSPA8 (0.17~0.60), CCNB1 (0.22~0.62) as the top five genes were highly correlated with glycolysis score across cancers." (PMID 32635458, 2020). "The expression heat map of P4HA1 and the Hub genes was displayed using the UCSC Cancer Genomics Browser." (PMID 33415167, 2020). "The same distribution as P4HA1, HSPA8 was also proved to be a factor influencing glycolysis score and key glycolysis genes expression in different hypoxia state across cancer types." (PMID 32635458, 2020).
cancer (continued). "P4HA1 expression promoted tumorsphere formation, expanded the ALDH-high cell population, and enhanced cancer cell colonization in the distant organs." (PMID 30367042, 2018). "By modulating alpha ketoglutarate (α-KG) and succinate levels P4HA1 expression reduces proline hydroxylation on hypoxia-inducible factor (HIF) 1α, enhancing its stability in cancer cells." (PMID 30367042, 2018). "In the xenografted tumors both P4HA1 and P4HA2 mRNA are found at similar levels in cancer cells and in stroma, contrasting the stroma-specific expression of P4HA3." (PMID 27809802, 2016). "In hypoxic fibroblasts HIF-1 induces extracellular matrix (ECM) remodeling by activating expression of P4HA1, P4HA2 and PLOD2 leading to changes in cancer cell morphology, adhesion and motility that promote invasion and metastasis." (PMID 25115393, 2014). "We and others have shown that P4HA1, an isoform of P4H, enhances the stability of hypoxia-inducible factor-1α (HIF-1α), a vital regulator of the cellular response to hypoxia, which promotes angiogenesis, cancer metastasis, and chemoresistance." (PMID 40694594, 2025). "Prolyl 4-hydroxylase (P4H) activity is essential for maintenance of the collagen triple helix and P4HAs (P4HA1, P4HA2, P4HA3) plus P4HB are highly expressed in numerous tumors where they may contribute to cancer progression." (PMID 35846138, 2022). "The prolyl 4-hydroxylase subunit alpha-1/alpha-2 (P4HA1/P4HA2) catalyzes the post-translational modification of 4-hydroxyproline in the -Xaa-Pro-Gly- sequence in various collagens and has been shown to be an important regulator in various cancers." (PMID 36572937, 2022). "Furthermore, CAFs (CAF1, CAF2) showed higher expression of specific markers including a-SMA, fibronectin, and P4HA1, compared with NFs (NF1, NF2) and cancer cells (DLD-1, HCT-116), indicating the successful establishment of CAFs." (PMID 34930899, 2021). "In addition, knockdown of P4HA1 inhibited the expression of MMP2 and MMP9, which were widely considered to relate to cancer invasion." (PMID 34659558, 2021). "In conclusion, our findings revealed that P4HA1 acts as an oncogene and a prognostic marker in pan-cancer and LUAD, and high P4HA1 expression might contribute to relative immunosuppressive microenvironment." (PMID 34966739, 2021). "By contrast, in cases of MSI cancer, P4HA1 expression did not significantly correlate with OS or DFS times." (PMID 32166002, 2020). "Prolyl 4-hydroxylase subunit alpha 1 (P4HA1) plays a crucial role in modulating extracellular matrix component and promoting tumor progression by changing tumor adhesion, migration, and other biological behaviors in some cancers." (PMID 33415167, 2020). "P4HA1 expression is also upregulated in HER2-positive tumor and cancer cell line." (PMID 30367042, 2018). "In addition, targeting genes upregulated under hypoxia in our study, such as prolyl 4-hydroxylase subunit alpha 1 (P4HA1), promoted T cell memory and enhanced their systemic anti-cancer immunity, further highlighting the potential of our model for future therapeutic discovery." (PMID 41199316, 2025). "However, most studies on the biological role and function of P4HA1 are limited to a particular type of cancer, and a comprehensive pan-cancer study on P4HA1 has not been performed." (PMID 35812752, 2022). "However, a pan-cancer analysis of P4HA1 has not been performed." (PMID 35812752, 2022). "HIF-1α induces the expression of P4HA1, P4HA2, PLOD1, and PLOD2 in different cancer and non-cancer cell lines, and enhanced activities of these enzymes are associated with increased collagen deposition in cancer tissue." (PMID 37490147, 2023).
cancer (continued). "We discovered that the expression of P4HA1 was related to stage in several cancers, including ACC, CESC, HNSC, chromophobe RCC, papillary RCC, LUAD, and TGCT but not in other cancers." (PMID 35812752, 2022).
tumor (77 papers, 2011 to 2026). "Risk score = 0.268 ∗ P4HA1 - 0.168 ∗ CCDC148 + 0.094 ∗ UCA1 + 0.054 ∗ TMPRSS11E + 0.31 ∗ Tumor Stage." (PMID 41080752, 2025). "This study aims to investigate the effects of Prolyl 4‐hydroxylase subunit alpha‐1 (P4HA1) inhibition on CRC tumor growth, metastasis, and tumor‐associated macrophage (TAM) infiltration." (PMID 41469036, 2025). "In this context, the next promising protein that is associated with hypoxia and tumor micromilieu is the prolyl 4-hydroxylase subunit α1 (P4HA1), which encodes the active catalytic component of prolyl 4-hydroxylase (P4H)." (PMID 40535577, 2025). "P4HA1 is associated with CRC progression and tumor immune infiltration; P4HA1 knockdown reduces CCL2, CCL4, CCL7 secretion and TAMs recruitment." (PMID 41469036, 2025). "Next, we utilized GEPIA2 to combine the expression data of all tumor types in TCGA and obtained 100 main genes linked to the expression of P4HA1." (PMID 35812752, 2022). "We also identified a strong correlation between P4HA1 expression and immune checkpoint gene expression, microsatellite instability, and tumor mutation burden in chromophobe RCC." (PMID 35812752, 2022). "We analyzed the association between P4HA1 expression and immune cell infiltration in different tumor types." (PMID 35812752, 2022). "The results revealed that elevated P4HA1 expression was associated with worse tumor stages in seven tumor types." (PMID 34966739, 2021). "Based on hazard ratio, P4HA1 overexpression increased death risk in patients with different tumor types in the following order: KICH > THCA > UVM > MESO > KIRP > CESC > ACC > PAAD > LUAD > HNSC > SARC > BRCA." (PMID 34966739, 2021). "Concerning the relations in P4HA1 protein expression and clinicopathological features, we found P4HA1 protein expression presented association with only tumor diameter, which consistent with the mRNA results." (PMID 34659558, 2021). "Intriguingly, we observed that GBM was the only tumor in which DNA methylation status on P4HA1 promoter was positively linked to its mRNA expression." (PMID 34966739, 2021). "We found that overexpression of P4HA1 was tightly associated with advanced clinical stage, larger primary tumor size, and shorter survival time." (PMID 33299876, 2020). "High P4HA1 expression in HNSCC tissues was significantly associated with tumor category, lymphatic metastasis and pathological stage." (PMID 31782831, 2020). "High P4HA1 protein expression was more frequently found in patients with poor (G3) tumor differentiation (p = 0.0084), mismatch repair loss (p < 0.0001), and right-sided location (p = 0.0025)." (PMID 32166002, 2020). "Since miR-124 had earlier been implicated as tumor-suppressor, we sought to determine its role in P4HA1 regulation by 3′-UTR luciferase assay." (PMID 25115393, 2014). "In addition, we investigated the correlation between P4HA1 expression and tumor mutation burden (TMB) and microsatellite instability (MSI)." (PMID 35812752, 2022). "In addition, we found that the promoter methylation level of P4HA1 was negatively linked to P4HA1 expression in 24 of 33 tumor types, which also induced high P4HA1 expression." (PMID 34966739, 2021). "Besides, we found that patients with high P4HA1 expression had a higher tumor mutation burden (TMB)." (PMID 34966739, 2021). "In addition, we discovered that P4HA1 expression was positively linked to tumor mutation burden (TMB) and microsatellite instability (MSI) in several tumor types, demonstrating a potential association with immunotherapy efficacy." (PMID 34966739, 2021). "Importantly, our study showed that overexpression of P4HA1 could be associated with tumor progression, invasion and thus act as a diagnostic biomarker of BC." (PMID 33692831, 2021). "P4HA1 regulates CD31 expression via COL6A1 during the transition of GBM stem‐like cells to tumor endothelial cells." (PMID 40226936, 2025).
tumor (continued). "P4HA1 exhibited high cytoplasmic/membranous staining intensity in tumor tissues, in contrast to weak expression in normal tissues." (PMID 40959429, 2025). "First, IHC with 90 paired CRC and normal adjacent tissues revealed that P4HA1 was mainly expressed in tumor cells, and significantly increased P4HA1 expression was noted in CRC tissues compared with tumor stroma or normal colon tissue." (PMID 41469036, 2025). "Specifically, analysis of proteomic data from the Human Protein Atlas (HPA) revealed that PDSS2, GRSF1, SLC39A8, and P4HA1 are markedly upregulated in tumor tissues compared to normal samples." (PMID 40959429, 2025). "In the same scRNA-seq dataset, we also assessed P4HA1 gene expression in PDAC tumor cells enriched in the hypoxia gene signature, further confirming the association of P4HA1 expression and hypoxia (fold change = 2.073, P = 4.188 × 10−126)." (PMID 40332386, 2025). "We first confirmed the correlation of P4HA1 with hypoxia in tumor cells from primary human PDAC tissue using scRNA-seq data." (PMID 40332386, 2025). "Specifically, PDSS2, GRSF1, SLC39A8 and P4HA1 were significantly upregulated in tumor tissues compared to normal samples." (PMID 40959429, 2025). "In this study, we interrogate the impact of hypoxia in a PDAC PDO model, identifying P4HA1 as a key mediator of tumor invasion in hypoxia." (PMID 40332386, 2025). "In vivo experiments confirmed that P4HA1 knockdown inhibited CRC tumor growth, metastasis, and TAM infiltration polarization." (PMID 41469036, 2025). "First, knocking down P4HA1 significantly inhibited tumor growth in the HT‐29 xenograft model in nude mice." (PMID 41469036, 2025). "The association between P4HA1 expression and CRC progression as well as tumor immune infiltration was analyzed." (PMID 41469036, 2025). "In vivo experiments were also carried out to verify the effect of P4HA1 knockdown on CRC tumor growth, metastasis, and TAM infiltration polarization." (PMID 41469036, 2025). "Immunohistochemical results were consistent with those from previous bioinformation analysis, and P4HA1 expression was significantly increased in tumor tissues compared with adjacent normal tissues." (PMID 38806556, 2024). "HIGD1A, EFHD1, and PPARGC1A were found to be overexpressed in normal tissue, whereas TRAP1 and P4HA1 were found to be overexpressed in CRC tumor tissue (p < .001)." (PMID 37903487, 2024). "In turn, HIF1 promotes structural rearrangements in ECM, dissemination of tumor cells, and metastasis by upregulating P4HA1 in CAF and tumor cells." (PMID 39329988, 2024). "We found that, compared to normal tissues, P4HA1 expression was significantly elevated in tumor stages III, IV." (PMID 38806556, 2024). "Given that P4HA1 is the major subtype of P4Hs3,32, we further investigated the expression of P4HA1 in clinical specimens and its role in tumor progression." (PMID 38806556, 2024). "The bioinformatics results suggest that P4HA1-3 was overexpressed in HNSC tumor tissues when compared with corresponding normal tissues." (PMID 38806556, 2024). "Because several tumor types did not have matching normal tissue data in TCGA, GEPIA was used to further analyze the expression of P4HA1 between tumor and normal tissues." (PMID 35812752, 2022). "Then, we examined the expression of P4HA1 across 33 different tumor types using the TCGA, CPTAC, GEO, and Oncomine databases." (PMID 35812752, 2022). "COL6A1, as a member of the collagen family, undertakes the main component of tumor ECMs, while P4HA1 can regulate the secretion of collagen, thus affecting the composition of ECM." (PMID 35494018, 2022). "We carried out a comprehensive analysis toward the latent biological role of P4HA1 (NM_001017962.3 for mRNA or NP_001017962.1 for protein) across tumor types." (PMID 35812752, 2022). "Under hypoxic tumor conditions, HIF-1 induces expression of genes that encodes collagen prolyl (P4HA1 and P4HA2) and lysyl (PLOD2) hydroxylases." (PMID 34249670, 2021).